PACS1 (phosphofurin acidic cluster sorting protein 1)
Description:
Coat protein that is involved in the localization of trans-Golgi network (TGN) membrane proteins that contain acidic cluster sorting motifs. Controls the endosome-to-Golgi trafficking of furin and mannose-6-phosphate receptor by connecting the acidic-cluster-containing cytoplasmic domain of these molecules with the adapter-protein complex-1 (AP-1) of endosomal clathrin-coated membrane pits. Involved in HIV-1 nef-mediated removal of MHC-I from the cell surface to the TGN. Required for normal ER Ca2+ handling in lymphocytes. Together with WDR37, it plays an essential role in lymphocyte development, quiescence and survival. Required for stabilizing peripheral lymphocyte populations (By similarity).
Synonyms: KIAA1175; FLJ10209; MRD17; SHMS
Tractability: Antibody: the Human Protein Atlas places it where antibodies can reach. PROTAC: ubiquitination databases record sites on it; its protein half-life has been measured.
Gene: Protein-coding gene on chromosome 11 (66,070,272 to 66,244,744, forward strand). Ensembl gene ENSG00000175115.
Subcellular location: Golgi apparatus, trans-Golgi network
Subcellular location (Human Protein Atlas): Plasma membrane; Nucleoplasm; Vesicles
Pathways (Reactome):
Disease: Nef mediated downregulation of MHC class I complex cell surface expression
Gene Ontology:
Molecular function: protein binding; transmembrane transporter binding
Biological process: protein localization to plasma membrane; lymphocyte homeostasis
Cellular component: cytosol; COPI-coated vesicle; Golgi apparatus
Genetic constraint (gnomAD): Loss-of-function variants: 17 observed, 85.01 expected, observed/expected ratio (o/e) 0.2, 90% interval 0.14 to 0.3. The upper end of that interval is the gene's LOEUF score, 0.3, which puts it in group 1 of 6, group 1 being the genes least tolerant of losing a copy. Missense variants: 724 observed, 1,072.2 expected, observed/expected ratio (o/e) 0.68, 90% interval 0.63 to 0.72. Synonymous variants: 412 observed, 432.41 expected, observed/expected ratio (o/e) 0.95, 90% interval 0.88 to 1.03.
Gene-disease validity (ClinGen):
ClinGen rates the evidence that PACS1 causes each of these diseases.
Schuurs-Hoeijmakers syndrome (autosomal dominant): Definitive.
Homologues: Orthologues: chimpanzee PACS1 (99% identical), mouse Pacs1 (97% identical), macaque PACS1 (97% identical), rat Pacs1 (96% identical), dog PACS1 (95% identical), guinea pig PACS1 (86% identical), pig PACS1 (86% identical), rabbit PACS1 (83% identical), zebrafish pacs1a (63% identical), tropical clawed frog pacs1 (59% identical), Drosophila melanogaster KrT95D (35% identical), Caenorhabditis elegans pacs-1 (24% identical). Paralogues in human: PACS2 (55% identical).
Diseases named in the same sentence as PACS1 in open-access papers:
PACS1 is named in the same sentence as 55 diseases in open-access papers, as found by Europe PMC text mining. Sharing a sentence is not in itself a finding about the gene and the disease. The quoted sentences say what the papers report.
Intellectual disability (12 papers, 2021 to 2025). "PACS1 syndrome is a neurodevelopmental disorder characterized by intellectual disability and distinct craniofacial abnormalities resulting from a de novo p.R203W variant in phosphofurin acidic cluster sorting protein 1 (PACS1)." (PMID 38280846, 2024). "In 2012, two cases were described secondary to a PACS1 mutation, which involved intellectual disability, epilepsy, facial dysmorphism, and generalized hypotonia." (PMID 38540691, 2024). "Mutations in PACS1 cause a defect in cranial neural crest migration, which leads to intellectual disability." (PMID 35590387, 2022). "Schuurs-Hoeijmakers syndrome, an autosomal dominant disorder associated with mutations in the PACS1 gene, was initially identified in two unrelated children of European descent from a cohort of individuals with intellectual disabilities." (PMID 36415352, 2022). "PACS1-NDD was first identified when two individuals with similar dysmorphic features, and intellectual disability presented with the same de novo mutation in the PACS1 gene." (PMID 34517877, 2021). "Background/Objectives: Schuurs–Hoeijmakers syndrome (SHMS), also known as PACS1 neurodevelopmental disorder, is a rare condition characterized by intellectual disability, distinctive craniofacial abnormalities, and congenital malformations." (PMID 40004556, 2025). "PACS1, PACS2, and WDR37 variants are associated with multisystemic syndromes and neurodevelopmental disorders characterized by intellectual disability, seizures, developmental delays, craniofacial abnormalities, and autism spectrum disorder." (PMID 39031646, 2024). "Both PACS1 and PACS2 mutations have been reported to be associated with neurological disorders: early onset epilepsy, intellectual disability, global developmental delay, and different malformations." (PMID 38540691, 2024). "One such gene is PACS1, which encodes the multi-functional trafficking protein PACS1 (or PACS-1); a single recurrent de novo missense mutation, c607C>T (PACS1R203W), causes developmental delay and intellectual disability (ID) 5,6." (PMID 36747781, 2023). "Schuurs–Hoeijmakers syndrome (SHMS) or PACS1 Neurodevelopmental disorder is a rare disorder characterized by intellectual disability, abnormal craniofacial features and congenital malformations." (PMID 34068396, 2021). "PACS1 neurodevelopmental disorder (PACS1-NDD) is a category of rare disorder characterized by intellectual disability, speech delay, dysmorphic facial features, and developmental delay." (PMID 34373684, 2021). "Schuurs-Hoeijmakers syndrome (SHMS), or PACS1 neurodevelopmental disorder (PACS1-NDD) (MIM# 615009), is a recently described rare autosomal dominant disease associated with developmental delay and intellectual disability." (PMID 37373745, 2023). "Schuurs–Hoeijmakers syndrome or PACS1 Neurodevelopmental disorder (MIM# 615009) is a rare autosomal dominant disease characterized by distinctive craniofacial features, intellectual disability (ID) with variable degrees of neurodevelopmental delay and congenital anomalies." (PMID 34068396, 2021).
epilepsy (5 papers, 2021 to 2025). A brain disorder characterized by episodes of abnormally increased neuronal discharge resulting in transient episodes of sensory or motor neurological dysfunction, or psychic dysfunction. "Epilepsy-associated genes (TPP1, BCKDK, ALG3, and PACS1) were upregulated and enriched in PZ and showed higher expression in the TLE as compared with the healthy control scRNA data." (PMID 39541170, 2025). "Mutation or altered expression of PACS proteins are associated with conditions ranging from cancer, obesity and viral pathogenesis to epilepsy and neurodegenerative disorders; however, the regulation mechanism of PACS-1 is still unknown." (PMID 36362413, 2022). "Rather than a form of epilepsy or epileptic encephalopathy, PACS1-NDD appears to be better described as an intellectual disability syndrome, perhaps akin to Down syndrome in terms of severity in intellectual and functional impairment." (PMID 34517877, 2021). "Seizures are a common trial outcome; however, a large proportion of children with PACS1-NDD do not have seizures, and most of those who have a history of epilepsy have well-controlled seizures." (PMID 34517877, 2021).
Neurodevelopmental delay (4 papers, 2021 to 2025). "Pathogenic variant sites on PACS1 and PACS2 have been associated with neurodevelopmental delay, seizures, behavioral issues, and microcephaly." (PMID 40533307, 2025). "Mutations in human PACS1 and PACS2 cause human neurodevelopmental disorders, characterized by epileptic seizures and neurodevelopmental delay." (PMID 39999877, 2025). "PACS1 neurodevelopmental disorder (PACS1-NDD) or Schuurs-Hoeijmakers syndrome (SHMS; MIM#615009) is a rare disease with typical mild-to-severe neurodevelopmental delays and mental retardation." (PMID 34373684, 2021).
Schuurs-Hoeijmakers syndrome (4 papers, 2021 to 2023). "The PACS1 pathogenic variant in association with the clinical findings confirmed the diagnosis of Schuurs-Hoeijmakers syndrome." (PMID 34468556, 2022). "In this paper, we report a novel variant of PACS1 associated with Schuurs-Hoeijmakers syndrome: a boy aged two years and nine months of indigenous descent presenting with motor stereotypies, atypical sensory searches, language delay, and low socio-interactional reciprocity." (PMID 36415352, 2022). "Notably, there were only two unique missense mutations [c.607C > T (p.Arg203Trp) and c.608G > A (p.Arg203Gln)] in PACS1 that had been identified as pathogenic variants for PACS1-NDD or Schuurs-Hoeijmakers syndrome (SHMS)." (PMID 34373684, 2021).
Obesity (3 papers, 2020 to 2025). Accumulation of substantial excess body fat. "Pacs1 may also affect the function of cilia, a structures that when altered are associated with development of obesity." (PMID 32356724, 2020). "We also found three KO strains which might protect from obesity, Pepd-/-, Klf12+/-, and Pacs1+/-." (PMID 32356724, 2020).
Alzheimer disease (2 papers, 2021 to 2022). A progressive, neurodegenerative disease characterized by loss of function and death of nerve cells in several areas of the brain leading to loss of cognitive function such as memory and language. "PACS1 has been reported to be associated with many diseases, including acquired immune deficiency syndrome (AIDS) and Alzheimer’s disease." (PMID 35590387, 2022). "PACS1 is also involved in the transport of amyloid precursor protein and enhances the formation of brain plaques in Alzheimer’s disease." (PMID 35590387, 2022).
cholangiocarcinoma (2 papers, 2020 to 2022). A carcinoma that arises from the intrahepatic biliary tree (intrahepatic cholangiocarcinoma) or from the junction, or adjacent to the junction, of the right and left hepatic ducts (hilar cholangiocarcinoma). "Our analysis suggests that expression of DEPDC1, FUT4, MDK, PACS1, PIWIL4, miR-22, miR-551b, and DNA methylation of cg27362525 and cg26597242 could be explored further as potential biomarkers of cholangiocarcinoma." (PMID 33193605, 2020).
gastric cancer (2 papers, 2018 to 2020). A primary or metastatic malignant neoplasm involving the stomach. "This study highlights the potential of using PCAF, ADA3, and PACS1 as biomarkers for early invasive gastric cancer and possibly, to predict response to cancer drugs that activate the mitochondrial cell death pathway." (PMID 29670108, 2018). "At the protein level, PCAF, ADA3, and PACS1 expression were all significantly down-regulated in intestinal-type gastric cancer, and correlated with reduced progression free survival." (PMID 29670108, 2018). "Our report is the first to link reduced PACS1 levels with gastric cancer." (PMID 29670108, 2018).
Macrocephaly (2 papers, 2014 to 2024). Occipitofrontal (head) circumference greater than 97th centile compared to appropriate, age matched, sex-matched normal standards. "Participant 178 is a 14-month-old male with macrocephaly and two ROHs on chromosomes 2 and 11 involving the HSPD1, PACS1, NDUFV1, and NDUFS8 genes that may play a role in psychomotor delay, hypotonia, and atypical development." (PMID 25400949, 2014). "All this suggests that p.R203W PACS1 does not affect early proliferation and specification dynamics during cortical development, which is in line with no consistent clinical reports of microcephaly or macrocephaly in PACS1 syndrome patients." (PMID 38280846, 2024).
Arrhythmia (1 paper, 2021). Any cardiac rhythm other than the normal sinus rhythm. "Multivariate regression showed that PACS1-day was an independent risk factor of arrhythmia recurrence." (PMID 34116696, 2021). "We found that the cut-off value of -12% for the PACS1-day had an area under the curve (AUC) of 0.6574 (p = 0.003); with sensitivity of 67.7% and specificity of 60.5% to predict arrhythmia recurrence." (PMID 34116696, 2021).
Cognitive impairment (1 paper, 2023). Abnormal cognition is characterized by deficits in thinking, reasoning, or remembering. "This expression pattern is in line with the main clinical characteristics of PACS1-NDD patients: cognitive impairment, dysmorphic facial features, and congenital malformations." (PMID 37373745, 2023).
colitis (1 paper, 2017). Inflammation of the colon. "In contrast to our findings in the DSS-induced colitis model, Pacs2-deficiency did not affect the small intestinal expression of PACS-1." (PMID 29312533, 2017).
coloboma (1 paper, 2025). An abnormality in which a part of a structure in one or both eyes is missing. "Ocular abnormalities like corneal opacity and coloboma are more frequent in WDR37 cases but have also been reported with PACS1 and PACS2 variants." (PMID 40869285, 2025).
Cornelia de Lange syndrome (1 paper, 2023). A rare syndrome characterized by low birth weight, delayed growth, intellectual disabillity, behavioral problems, and a distinctive facial appearance (thin, arched eyebrows, low set ears, small teeth, and small nose). "Initially, similarities between the facial features of PACS1-NDD and Cornelia de Lange syndrome (CdLS) were identified, and a clinical diagnosis of CdLS was even suggested for the first two patients reported to have PACS1-NDD." (PMID 37373745, 2023).
intellectual disability syndrome (1 paper, 2021). "PACS1-NDD is a moderately-severe intellectual disability syndrome in which seizures occur but are not a defining or primary feature." (PMID 34517877, 2021).
Kabuki syndrome (1 paper, 2023). Kabuki syndrome (KS) is a multiple congenital anomaly syndrome characterized by typical facial features, skeletal anomalies, mild to moderate intellectual disability and postnatal growth deficiency. "In fact, in syndromic disorders that are clinically comparable to PACS1-NDD, such as CdLS, Kabuki syndrome, and WDR37 syndrome, the prevalence of CHD has been estimated to be 33%, 50%, and 70%, respectively." (PMID 37373745, 2023).
Kleefstra syndrome (1 paper, 2017). A genetic disorder characterized by intellectual disability, childhood hypotonia, severe expressive speech delay and a distinctive facial appearance with a spectrum of additional clinical features. "The majority of clinicians would have limited experience diagnosing the recently characterised Kleefstra syndrome and PACS1." (PMID 29258477, 2017).
meningioma (1 paper, 2020). A generally slow growing tumor attached to the dura mater. "The corresponding transcript levels were validated for PACS1, LAMP2, HTRA1 and CST3 in meningioma tissue." (PMID 33167358, 2020). "Following RT-qPCR, we identified a significant reduction in relative expression for CST3, LAMP2, PACS1 and HTRA1 in grade III meningioma compared with grade I compatible with our hypothesis that increased abundance of these proteins in the tumour originates from the blood circulation." (PMID 33167358, 2020). "Notably, we derived a plasma signature of 21 discordantly expressed genes showing positive changes in protein but negative in transcript levels of high-grade meningiomas, including the validated genes CST3, LAMP2, PACS1 and HTRA1, suggesting the acquisition of these proteins by tumour from plasma." (PMID 33167358, 2020).
neurodevelopmental disorder (10 papers, 2021 to 2025). A behavioral and cognitive disorder with onset during the developmental period that involves impaired or aberrant development of intellectual, motor, or social functions. "PACS1 syndrome is a neurodevelopmental disorder resulting from a de novo p.R203W variant in phosphofurin acidic cluster sorting protein 1 (PACS1)." (PMID 38280846, 2024). "PACS1 syndrome is a neurodevelopmental disorder (NDD) caused by a recurrent de novo missense mutation in PACS1 (p.Arg203Trp (PACS1R203W))." (PMID 37848409, 2023). "SHMS or PACS1 Neurodevelopmental disorder was first reported in 2012 and it is a rare cause of ID." (PMID 34068396, 2021). "The Schuurs–Hoeijmakers syndrome (SHMS), or PACS1 Neurodevelopmental Disorder (PACS1-NDD) (MIM# 615009), is a rare autosomal dominant disease, which has recently been included in a group of genetic disorders of cellular trafficking." (PMID 36077045, 2022). "PACS1-Neurodevelopmental Disorder (PACS1-NDD) is an ultra-rare condition due to a recurrent mutation in the PACS1 gene." (PMID 34517877, 2021). "Our findings based on 35 children with documented PACS1 R203W mutations largely support the initial description by Schuurs–Hoiejmakers and a separate description of 16 patients by Seto of PACS1-NDD as a moderately severe neurodevelopmental disorder." (PMID 34517877, 2021). "Furthermore, most of the patients have been described in the last few years, when the PACS1 gene was included in the gene panel analysis for neurodevelopmental disorders; therefore, it is possible that the prevalence of this syndrome could be underestimated." (PMID 36077045, 2022). "Since 2012, when PACS1-NDD was first characterized, deep phenotyping analysis has allowed us to establish a potential relationship with other neurodevelopmental disorders, such as the PACS2 or Wdr37 syndromes." (PMID 36077045, 2022).
cancer (5 papers, 2018 to 2025). A tumor composed of atypical neoplastic, often pleomorphic cells that invade other tissues. "Mutation or deletions of the PACS1 gene locus at chromosome 11q13.1 has been associated with the development of several cancers including cervical cancer." (PMID 29670108, 2018). "Specifically, PACS1 has been implicated in apoptosis through its regulation of BAX and BAK, highlighting its potential impact on cancer cell survival and treatment responses." (PMID 40728977, 2025). "Recent reports have suggested a role for PACS-1 in maintaining chromosomal integrity, with PACS-1 overexpression resulting in genomic instability of human cancer cells." (PMID 36362413, 2022). "These genes are involved in the regulation of cell cycle (CCND1, CDCA5, FOSL1, KDM2A, NUMA1, RHOD), apoptosis (FADD, ORAOV1), or the DNA damage response (DDB1, KAT/TIP60, MUS81, PACS1, RPS3), and several have been implicated in the HPV lifecycle and/or HPV-associated cancers." (PMID 40892869, 2025). "The (PACS-1)-dependent protein-sorting pathway, with its implication in genomic instability, could represent a novel crucial event in asbestos-related cancer development since its impairment seems to be exclusive to asbestos-exposed individuals who did not develop LC or MPM." (PMID 36362413, 2022). "The recently demonstrated pro-apoptotic properties of PACS1 and PACS2 and their transcriptional regulation by ADA3 and PCAF suggests that the four proteins (and possibly others) constitute a novel signaling pathway that acts to suppress the formation of gastric (and possibly some other) cancers." (PMID 29670108, 2018).